HIF1A (hypoxia inducible factor 1 subunit alpha)
Diseases named in the same sentence as HIF1A in open-access papers (continued):
Sharing a sentence is not in itself a finding about the gene and the disease.
tumor (continued). "Such positive-regulatory co-operation of HIF-1α, miR-210, and TIMP-1, all described to correlate with bad prognosis of cancer patients, opens new perspectives of gaining insight into molecular mechanisms of metastasis-inducing evasion of tumor cells from stress." (PMID 22807917, 2012). "These novel observations may indicate that KAI1 exerts profound metastasis-suppressor activity in the tumor malignancy process via inhibition of CDCP1-mediated Src activation, followed by VHL-induced HIF-1α degradation and, ultimately, decreased VEGF expression." (PMID 22390300, 2012). "We have clearly documented that the hypoxia-mediated HIF-1α-dependent up-regulation of NRP-1 not only confers the angiogenic properties on the HT1080 cells leading to vasculogenic mimicry, but also augments their tumour-forming ability, thereby acting as a double-edged sword in these cells." (PMID 23185562, 2012). "Once stabilized, HIF-1α translocates into the nucleus, dimerizes with HIF-1β, and activates the transcription of target genes such as Vascular Endothelial Growth Factor (VEGF) and Nitric Oxide Synthase 2 (NOS2), which are highly related to tumor growth and survival." (PMID 23166763, 2012). "In tumor cells, high levels of glucose induce the accumulation and expression of HIF-1α, whereas non-tumor cells exhibit decreased HIF-1α accumulation in response to high glucose, suggesting that impaired glucose homeostasis directly affects angiogenic signals within tumors." (PMID 22853690, 2012). "However, it did not downregulate HIF-1α or reverse EMT of tumor cells under hypoxic conditions in vitro." (PMID 23137165, 2012). "Second, it is not clear how and why HIF-1α expression, which is the most influential factor affecting intratumoral pH, cell cycle status, oxygen-consumption, and moreover tumor radioresistance etc., is suppressed under hypoxic conditions when the glucose concentration is low." (PMID 23203043, 2012). "However, H1339 and EPLC-272H tumor cells express similar amounts of RACK1 and also sequence analysis did not reveal any mutations in the PAS-A domain of HIF-1α in H1339 cells." (PMID 22347438, 2012). "Moreover, in line with our observations in TAMs, tumor-cell–conditioned medium induced Hif1α, VefgA and Mmp9 expression in control but not in Mφ-c-Myc-KO BMDMs." (PMID 23028984, 2012). "Collectively, the expression of Pgp and Hif-1α was elevated in the perimeter of tumors established from hypoxic cells relative to the core while the perimeter of tumors established from normoxic cells had lower expression of EGFR and higher expression of GLUT-1 relative to the tumor core." (PMID 21320311, 2011). "At present, the mechanism regulating HIF-1α is still not fully clear in hypoxic tumor cells." (PMID 21595915, 2011). "Therefore, we demonstrate that miR-21 induces tumor angiogenesis through targeting PTEN, leading to activate AKT and ERK1/2 signaling pathways, and thereby enhancing HIF-1α and VEGF expression; HIF-1α is a key downstream target of miR-21 in regulating tumor angiogenesis." (PMID 21544242, 2011). "In addition, hypoxia-inducible factor-1 alpha (HIF-1α), a critical transcription factor in the mammalian oxygen-sensing pathway, is activated in response to hypoxia, altering tumor xenograft gene expression, growth, and angiogenesis possibly through membrane type 1 metalloprotease." (PMID 21827650, 2011). "Interestingly, HIF-1α and HPV16 E7 immunoreactivity were uniform in location on the same tumor, and their labeling indexes showed a significantly positive correlation (Rho = .512; p < .001), which suggested a positive association between HPV16 E7 and HIF-1α expression." (PMID 22032288, 2011). "HIF-1α is overexpressed in solid tumors due to intratumoral hypoxia, genetic alterations, or both, and thus may be a predominant regulator that contributes to elevated levels of PKM2 in human tumor tissues." (PMID 21709315, 2011).
tumor (continued). "HIF-1α expression is also elevated in most tumor cells whether or not hypoxia is present and could mediate in part aerobic glycolysis." (PMID 20181022, 2010). "Apart from its pro-apoptotic, growth inhibitory, and anti-angiogenic properties, this could be, at least in part, due to downregulating tumour progression and invasion-related genes (u-PAR, HIF1α, and VEGFC) and upregulating NSCLC tumour-related suppressor genes (FHIT, RASSF1, and VHL) by Enz." (PMID 20736951, 2010). "Furthermore, the capacity of SOD1 to promote angiogenesis through activation of HIF1α-mediated VEGF expression could potentially play a role in tumor progression." (PMID 20064251, 2010). "Not all tumours with necrosis showed perinecrotic HIF-1α expression." (PMID 20565904, 2010). "Importantly, these effects were downregulated both by hypoxia and by HIF-1α, whose stabilization obtained with either CoCl2 or by using proteasome inhibitor (Z-LLF) was preventing BMP2 induced Akt/mTOR activation, especially in tumor cells." (PMID 19587783, 2009). "In addition, hypoxia seemed not to change HIF-1α mRNA expression of tumor cells, evaluated by real time RT-PCR." (PMID 19893619, 2009). "Knockdown of HIF-1α did not yield a corresponding decrease in tumor burden at time of death." (PMID 19727403, 2009). "HIF-1α and VEGF could be biomarkers indicating tumor infiltration and metastasis evaluation in CRC." (PMID 20003271, 2009). "Notably, comparable with the EGC samples, tumour-infiltrating inflammatory cells steadily showed a specific nuclear HIF-1α staining (not shown)." (PMID 19223895, 2009). "This suggests that pro-differentiating agents, such as BMPs, may promote a metabolic shift toward oxidative phosphorylation in tumor cells and that BMP2, by decreasing intracellular succinate through induction of SHD activation, may increase PHD2 activity leading to HIF-1α modulation." (PMID 19587783, 2009). "Nevertheless, we verified in the in vivo model that tumor cells were growing in a hypoxic environment by measuring the mRNA levels of well-known HIF-dependent genes such as PDK1 or VEGF, which are controlled by a hypoxia response element (HRE) in their promoters, as well as the HIF-1α expression." (PMID 19956670, 2009). "HIF-1α activates the transcription of vascular endothelial growth factor (VEGF), a key factor in tumor angiogenesis, and the expression of glucose transporters, glycolytic enzymes, and growth factors, which may promote tumor cell survival under hypoxic conditions." (PMID 18452596, 2008). "Due to the fact that in benign tissue HIF-1α is not detected, the expression in tumor tissue could arise from genetic alterations." (PMID 18983642, 2008). "As HIF-1α and HIF-2α have contrasting properties, a possible switch to HIF-2α could increase the likelihood to proliferation and survival, during tumour evolution." (PMID 17505508, 2007). "This existing knowledge suggests that HIF-1α may be a good indicator of tumor response to EGFR-targeted therapy, but to date no studies have investigated this possibility." (PMID 17931419, 2007). "In 83 tumour sections (47%), no HIF-1α nuclear immunostaining was observed." (PMID 17179985, 2007). "However, some reports have suggested that tumor expression of HIF-1α does not confer a survival advantage." (PMID 17166265, 2006). "Therefore these findings suggest that tyrosine kinase receptor activation and/or a response to hypoxia, leading to increased HIF-1α, is critical for the regulation of the expression of CXCR4, and may represent a general scheme in tumor metastasis." (PMID 17083723, 2006).
tumor (continued). "A major driver of the biology of hypoxic tumours is the transcription factor HIF-1α, which is responsible not alone for altered gene expression, but also may contribute to cancer progression and the development of a phenotype more refractory to therapy." (PMID 16333244, 2005). "The expression of vascular endothelial growth factor (VEGF), HIF-1α, HIF-2α and carbonic anhydrase 9 (CA9) was examined by immunohistochemistry in 45 patients with PETs and compared to microvascular density (MVD), endothelial proliferation, tumour stage and survival." (PMID 15558070, 2005). "In some tumours, overexpression of HIF1α was not accompanied by LDH-5 overexpression." (PMID 12942121, 2003). "Although HIF-1α was not an independent unfavourable prognostic factor, its expression may strongly influence both tumour proliferation and lymph node metastasis in OSCC." (PMID 12966423, 2003). "However, it was shown that comparing HIF1A to EPAS1 proteins, despite their primary role as transcription factors for cellular response to hypoxia, could play independent or/and coregulatory roles in tumor physiology and progression." (PMID 39888575, 2026). "While HIF-1α promotes angiogenesis, glycolysis, and immunosuppression via programmed death-ligand 1 (PD-L1) upregulation and myeloid-derived suppressor cell (MDSC) recruitment, HIF-2α exhibits context-dependent functions, which may include tumor-suppressive roles in certain settings." (PMID 41531732, 2026). "Thus, inducing HIF-1α-mediated expression of angiogenic growth factors such as VEGF-A, basic fibroblast growth factor (bFGF), placenta growth factor (PlGF), and platelet-derived growth factor (PDGF) results in aberrant vascularization and tumor hypoxia, leading to GBM progression." (PMID 41155273, 2025). "Therefore, we propose that inhibiting SIRT5’s desuccination activity on PPA2 could specifically target HIF-1α for ubiquitination and degradation in tumor cells without affecting normal cells." (PMID 40164945, 2025). "Since Mint3 conveys hypoxia-induced tumor growth signaling without hypoxic accumulation of HIF-1α, it is plausible that Mint3 activation might be the initial step toward moderately differentiated HCC development from dysplastic nodules or well-differentiated HCC." (PMID 40003897, 2025). "Importantly, in line with our cell culture-based assays, HIF1A silencing or inhibition of glucose uptake with the GLUT1 inhibitor WZB117 was sufficient to suppress the metabolic changes and reduce both the number of tumor nodules and the metastatic area in mice injected with RNF20 + /- A549 cells." (PMID 40436847, 2025). "However, the higher expression of HIF-1α can also induce the expression of vascular endothelial growth factor (VEGF) and other genes, which leads to the increase of tumor angiogenesis and local tumor microcirculation perfusion, and dilutes tumor local acidity to some extent." (PMID 40444079, 2025). "In addition, CCL5 secreted by CAFs promotes metastasis by activating the HIF1α/ZEB1 axis in HCC cells, whereas herbal components such as glycyrrhizic acid may inhibit the interaction of CAFs with tumour cells and reduce the release of immunosuppressive factors." (PMID 40495147, 2025). "Moreover, the presence of HIF-1α protein in non-hypoxic tumor regions suggests that other factors may indirectly affect glucose metabolism and 18F-FDG uptake in these regions." (PMID 40283896, 2025). "Additionally, HIF-1α induces the expression of target genes, such as VEGF, GLUT-1, Matrix Metalloproteinase 9 (MMP-9), Stromal Cell-Derived Factor 1 alpha (SDF-1α), and BNIP3, further driving tumor angiogenesis, metabolic reprogramming, and anti-apoptotic processes." (PMID 40443737, 2025). "Finally, we attempted to conduct a therapeutic model by clarifying whether or not a ketogenic diet combined with a HIF-1α inhibitor 3-(5′-hydroxymethyl-2′-furyl)-1-benzylindazole (YC-1) effectively suppresses HCC tumor growth in mice." (PMID 41465202, 2025).
tumor (continued). "However, HIF-1α may also induce VEGF overexpression, leading to tumor neoangiogenesis." (PMID 40227577, 2025). "Furthermore, HIF-1α suppresses mitochondrial fatty acid oxidation by inhibiting medium-chain acyl-CoA dehydrogenase (MCAD) and long-chain acyl-CoA dehydrogenase (LCAD), reducing ROS production and blocking the PTEN pathway, which ultimately favors tumor cell proliferation." (PMID 40813760, 2025). "No statistical difference could be seen with the age, sex, tumor grade and tumor size, however, patients presented with LNs involvement in N1 had statistically higher HIF1-α expression (2.492) when the VEGF expression in endothelium was positive, but this result was not seen for N2 (1.797)." (PMID 38313904, 2024). "We considered it necessary to test the efficacy of NPs to deliver HIF-1α siRNA2 to solid tumors in vivo with the goal of assessing whether it was possible to downregulate HIF-1 and its downstream oncogenic genes in a complex and heterogeneous tumor microenvironment." (PMID 39458615, 2024). "However, in contrast to previously established findings that suggested HIF-1α stabilization in VHL-KO or PHD-KO mouse models enhances T-cell responses, the effect of HIF-1α stabilization after CD8 T cell activation on their anti-tumor responses remains uncertain." (PMID 39242595, 2024). "In addition, hypoxia induces HMGB1 expression in mouse and human HCC cells in a HIF-1α-dependent manner, driving TAM recruitment and polarisation and elevating IL-6 concentrations, which further exacerbates EMT, vascular invasion, and the metastasis of HCC tumours." (PMID 39684877, 2024). "Therefore, the absence of HIF-1α would not appear to benefit the tumor cell." (PMID 39048564, 2024). "Also, in vivo and pilot clinical studies have reported HIF-1α or VEGF immunophenotypes fitted with the correlation of PET-imaging and/or MRI, supporting the combined macroscopic evaluation with histopathological features in monitoring and distinguishing GBM tumor progression from pseudoprogression." (PMID 39055895, 2024). "Additionally, tumor cells in hypoxic environment also release tumor suppressor protein M (oncostatin M) and eosinophilic chemotactic factor (eotaxin or CCL11), which promote macrophage infiltration into TME and polarization into M2-like phenotype driven by HIF-1α." (PMID 39606239, 2024). "Besides, recent studies found that dietary and herbal compounds, such as apigenin and a synthetic derivative of curcumin called CDF (a novel curcumin-derived synthetic analogue), could simultaneously inhibit HIF-1α and EZH2, reducing cancer invasiveness and improving tumor prognosis." (PMID 38911968, 2024). "In addition, targeting HIF-1α could potentiate PD-1/PD-L1 immunotherapy by increasing normal tissue immune tolerance and immune-induced tumor regression, as well as reducing immune-related adverse events." (PMID 37828561, 2023). "Also, the HIF-1α protein that can be observed in non-hypoxic tumor regions suggests that other factors may indirectly influence glucose metabolism and [18F]-FDG uptake in these regions." (PMID 36844199, 2023). "Furthermore, we found that DOKD inhibited CT26+ tumor cell growth by regulating inflammation, metastasis, and angiogenesis by activating the IL-17/TLR4/NF-κB p65 pathway and inhibiting the activation of the Src/HIF-1α/Erk1/2/Snail/N-cadherin/Vimentin/MMP9 and Erk1/2/HIF-1α/STAT3/VEGFA pathways." (PMID 37239383, 2023). "Stabilized HIF-1α binds its partner HIF-1β and translocates to the nucleus triggering a cascade of downstream signalling to mitigate hypoxia-mediated death, preserve metabolites the tumor cells may need, and promote tumor cell migration so the cells can escape from the area of hypoxia." (PMID 37631236, 2023).
tumor (continued). "Using the patient-derived nonembolized tumor primary cell culture, the effects of a hypoxia mimetic cobalt chloride (CoCl2) and an activator of the AhR signaling pathway benzo(α)pyrene (B[a]P) on mRNA levels of HIF-1α, AhR, and their target genes were investigated." (PMID 37305351, 2023). "Furthermore, HIF1α directly regulates NRP1 expression in cells exposed to a hypoxic microenvironment, suggesting a role for HIF1α-induced hypoxic responses in promoting lenvatinib resistance, particularly when the silencing of HIF1α enhances the anti-tumor effects of lenvatinib." (PMID 36769116, 2023). "Interestingly, HIF-2α, but not HIF1α, mainly mediates the induction of ferroptosis in tumor cells." (PMID 37048123, 2023). "In addition, non-hypoxic-HIF-1α might be the critical player to hatch from the occult dormancy of GBM after surgical removal or tumor treatment." (PMID 36183290, 2022). "Moreover, ICI analysis further indicated that HIF-1α was positively correlated with multiple immune cells, especially with CD4+, CD8+, and γΔ T cells, and the corresponding phenomenon was also validated in tumor tissues with high-throughput sequencing and immunofluorescence staining experiments." (PMID 36091021, 2022). "Indeed, while the tumor-derived secreted factors induced HIF1α in the monocytes, the inhibition of HIF1α via siHIF1α and echinomycin attenuated CA12 expression, demonstrating that activation of the HIF1α pathway provides a molecular link between the acidic environment and CA12 expression." (PMID 35362482, 2022). "Thus, both the NF-κB/HIF-1α and IRF/TLR/STAT signaling pathways could be targeted in cancer to prevent cancer cells from persistently shifting macrophages into TAMs, which favor cancer progression within the tumor microenvironment." (PMID 35327484, 2022). "Pulmonary thrombosis did not alter tumor apoptosis in WT or conditional KO mice but did approximately double the levels pulmonary tumor proliferation and vascularisation, and these microbead-induced increases were absent in myeloid HIF1α KO mice and reduced in myeloid HIF2α KO mice." (PMID 36291563, 2022). "Regardless of whether tumor tissue is compared with its corresponding normal tissue, or at the level of organ cell lines, the mRNA expression levels of HIF1α are higher in organs like the brain, digestive organs (esophagus, pancreas, stomach, and gallbladder), and lungs." (PMID 35860430, 2022). "Similarly, hypoxia induced the upregulation of angiopoietin-like 4 (ANGPTL4), HIF-1α/COX-2 and miR-135b and miR-210 in the exosome cargo of A549 cells, exosome transfer of these factors to other A549 cells led to the enhanced proliferation, migration, angiogenesis, and tumor progression." (PMID 35444652, 2022). "A possible explanation for this strong relationship between HIF-1α overexpression and tumor clinicopathologic factors could be the direct regulatory effect of HIF-1α on the vascular endothelial growth factor (VEGF) gene which is responsible for tumor angiogenesis." (PMID 35845307, 2022). "PI3K upregulates HIF-1α protein synthesis via AKT/mTOR and the eukaryotic translation initiation factor 4E (eIF-4E) binding protein (4E-BP1) Nevertheless, the activation of AKT could also lead to increased HIF-1α expression in tumor cells via another pathway that is independent of mTOR activation." (PMID 34830491, 2021). "Moreover, transcription factor hypoxia-inducible factor 1-alpha (HIF1α) and the biological interaction between HER2 and CD44 may lead to upregulation of C-X-C chemokine receptor type 4 (CXCR4), which promotes tumor progression and NCRT resistance in gastroesophageal cancer." (PMID 33151397, 2021). "Moreover, PFKFB3 expression can be regulated by oncogenes like hypoxia-inducible factor 1-alpha (HIF-1a), RAS, mesenchymal epithelial transition (MET), phosphoinositide 3-kinases (PI3K/Akt), and phosphatase and tensin homolog (PTEN) to provide metabolic control of tumor development." (PMID 34359849, 2021).